RAF1 (Raf-1 proto-oncogene, serine/threonine kinase)
Diseases named in the same sentence as RAF1 in open-access papers (continued):
Sharing a sentence is not in itself a finding about the gene and the disease.
tumor (continued). "We have established double‐knockout and single‐knockout nu/nu mice tumour models of Raf1‐Pkm2 and showed a significant reduction in tumour size with the double knockout of Raf1 and Pkm2, whereas single knockout did not result in a significant reduction in tumour size." (PMID 39073026, 2024). "Importantly, combination of Wnt inhibitor and RAF1/MEK inhibitor can suppress the tumor growth of patient-derived xenografts (PDXs) that have EIF3H/HAX1 overexpression." (PMID 38514606, 2024). "The tumor suppressive effect of miR-605-3p in OS progression was mediated by RAF1, thus indicating that miR-605-3p could be a potential therapeutic approach for OS treatment." (PMID 39076089, 2024). "In addition, we found that the interaction network involving JHDM1D/KDM7A was associated with RAF1, ARAF, JAK2, and CAMK2 activation, reinforcing the involvement of JHDM1D/KDM7A in tumor aggressiveness and progression." (PMID 39136575, 2024). "Differential expression of Raf1 and Pkm2 in tumour tissues and adjacent tissues." (PMID 39073026, 2024). "The activation of the MAPK signaling pathway may lead to tumor cell proliferation, differentiation, invasion and metastasis, accelerating the pathological process of tissue, while RAF1 is also highly expressed in many types of tumor cells." (PMID 37833936, 2023). "Our report expands the landscape of oncogenic RAF1 aberrations in various solid cancers, and increasing the recognition of RAF1 aberrations in tumors will assist in further refining tumor classification and hopefully guide the management of patients with tumors bearing these alterations." (PMID 38137485, 2023). "PBX3 could inhibit tumor cell apoptosis by activating the Raf1/MAPK1 pathway 43 and by suppressing tumor suppressor miRNAs, including miR-302, miR-129-5p, and miR-495 34-36." (PMID 37781025, 2023). "Several recent studies demonstrated that tumor-associated KRAS mutations, that result in abnormal activation of the RAS/Raf1/MEK/ERK pathway, can lead to multiple defects in the type I IFN signaling, thus making KRASMUT cancer cells more permissive to VSV and other OVs (59, –, 63)." (PMID 37671865, 2023). "The tumor specimens from a total of 77 patients (2.0%) had RAF1 aberrations." (PMID 38137485, 2023). "Sorafenib, also known as Nexavar, is a multi-targeted tyrosine kinase inhibitor (TKI) that inhibits tumor cell proliferation by inhibiting kinase activity in the B-Raf, Raf-1, and Ras/Raf/MEK/ERK signaling pathways and can also inhibit angiogenesis, as well as promote apoptosis of tumor cells." (PMID 37351514, 2023). "In vitro experiments suggested that decreased expression of RAF1 could inhibit proliferation, migration and invasion of tumor cells and promote apoptosis." (PMID 35668458, 2022). "Indeed, depletion of either ASK1 or MST2 was sufficient to revert the anti‐proliferative effect of RAF1 depletion in human tumor cell lines and PDX models." (PMID 34951114, 2022). "Notably, the requirement for RAF1 was not limited to tumor initiation, a usually less stringent condition, but extended to tumor progression and maintenance, thus indicating that RAF1 plays a crucial role in KRAS‐driven LUAD." (PMID 34951114, 2022). "Proteomic sequencing and subsequent experiments suggested that LAGE1 could promote development of tumor and lymphatic metastasis, and was regulated by RAF1." (PMID 35668458, 2022). "We also anticipate that RAF1 degradation could synergize with PD‐1 blockage given the increase in numbers of tumor‐infiltrating CD8+ T cells upon genetic RAF1 ablation alone." (PMID 34951114, 2022). "Hence, the significant levels of tumor regression observed upon RAF1 ablation are likely to be more limited upon RAF1 degradation in human patients." (PMID 34951114, 2022).
tumor (continued). "In conclusion, down-regulation of LAGE1 could also inhibit tumor growth and lymphatic metastasis, and this inhibition was more significant under RAF1 regulation." (PMID 35668458, 2022). "Above in vitro experiments proved that LAGE1 down-regulation could inhibit the proliferation, migration and invasion of tumor cells and promote apoptosis, while RAF1 inhibitor Sorafenib could further enhance this trend." (PMID 35668458, 2022). "Sorafenib is a multi-kinase inhibitor of Raf-1 and B-Raf, which can simultaneously inhibit a variety of intracellular kinases involved in tumor cell signal transduction, angiogenesis and apoptosis, and exert anti-tumor effects." (PMID 35069910, 2022). "The drug is inhibiting tumor cell proliferation and is blocking tumor angiogenesis via targeting kinases in various oncogenic signaling pathways such as Raf-1, Vascular endothelial growth factor receptor (VEGFR) and Platelet-derived growth factor receptor (PDGFR)." (PMID 35695930, 2022). "A study have revealed that activation of ADRB2 results in inhibition tumor cell growth, as well as induction of apoptosis and tumor regression, where this activation results in the inactivation of the Raf-1/Mek-1/Erk1/2 pathway by a cAMP-dependent activation of protein kinase A17." (PMID 36163241, 2022). "The pharmacological inhibition of PRMT5 by 5′-methylthioadenisine (MTA) or the inhibition of PRMT5 using ShRNA increased RAS-ERK1/2 activity in response to hepatocyte growth factor (HGF) and resulted in tumor suppressive effects by downregulating EGFR and RAF1 signaling in PC12 tumor cells." (PMID 33670008, 2021). "Interestingly, this study also showed that resistance to RAF1 or EGFR ablation separates two different groups of PDAC tumours at the molecular level." (PMID 33920182, 2021). "Importantly, this work showed that Ser338-phosphorylated RAF1 localised to the mitotic spindle in tumour samples." (PMID 33920182, 2021). "The oral multikinase inhibitor sorafenib (Nexavar®) suppresses tumor growth by targeting Raf serine/threonine kinases (Raf-1, wild-type B-Raf, and oncogenic B-Raf V600E) and receptor tyrosine kinases (VEGFR-1, VEGFR-2, VEGFR-3, PDGFR-β, Flt-3, and c-Kit) in a variety of human cancers." (PMID 33917906, 2021). "Sorafenib is an oral tyrosine kinase inhibitor (TKI) that targets kinases involved in angiogenesis and tumor proliferation pathways implicated in the molecular pathogenesis of HCC (i.e., Raf-1, B-Raf, vascular endothelial growth factor receptor 1–3, and platelet-derived growth factor receptor β)." (PMID 32674461, 2020). "Only RAF1 mRNA level showed a significant increase in tumor tissues compared background control." (PMID 32190741, 2020). "Our present study demonstrates that miRNA-7, known primarily to harbor tumor suppressive functions in diverse cancer types, and Rapidly Accelerated Fibrosarcoma 1 (RAF1), one of its targets, play essential roles in NPM-ALK+ ALCL, by controlling the autophagy flux and tumor cell fate." (PMID 33066037, 2020). "Application of HK peptides via intratumoral administration of Raf-1 siRNA to MDA-MB-435 tumor-bearing mice showed that siRNA nanoplexes formed by highly branched H3K8b were not particularly effective, yet the less branched H2K4b and H3K4b peptide were found to be the most effective carriers." (PMID 32961908, 2020). "Moreover, tumour tissues in Raf‐1 knock‐down groups showed suppressed proliferation and increased apoptosis, as demonstrated by Ki‐67 and TUNEL staining, respectively." (PMID 31541523, 2019).
tumor (continued). "Similar to our in vitro observations, depletion of Raf‐1 led to profound tumour growth arrest (shRaf‐1), whereas overexpression of p70S6K abolished this growth arrest (shRaf‐1 + OE‐p70S6K), which was further confirmed by comparing tumour weights between these two groups." (PMID 31541523, 2019). "Level of Rb-raf-1 interaction, Chk1 and Cdc2 expression ensures the cells survival, which relates to angiogenesis induction while Chk2 is a tumour suppressor and stimulated in response to DNA damage and replication blockage that occurred within the cancerous cells due to proliferation inhibition." (PMID 30728391, 2019). "Available literature reveals that TNK1 has both tumor suppressing and oncogenic potential as it can mitigate the growth of tumor cells by dowenregulating Ras-Raf1-MAPK pathway, induce apoptosis through NF-κB inhibition, activate cellular transformation and growth of neoplastic cells." (PMID 29455667, 2018). "Finally, we proved that CASZ1 exerted its tumor-suppressive effect by directly interacting with RAF1 and reducing the protein stability of RAF1." (PMID 29506567, 2018). "Furthermore, suppression of both MKK-7/c-Jun and Raf-1/Fra-1 activities was involved in the tumor growth inhibitory effects induced by SAHA in SH-SY5Y xenograft mice." (PMID 26734995, 2016). "Thus, RAF1 ablation in hepatocytes increased tumour multiplicity, whereas lack of RAF1 in non-parenchymal cells restrained inflammation leading to reduced tumour size." (PMID 28000790, 2016). "Our study defines a tumour suppressor role of RAF1 in hepatic carcinogenesis." (PMID 28000790, 2016). "In addition, the ratio of RAF1/YAP1 expression in the same tumour negatively correlated with histological grade in the whole cohort, indicating that tumours with low RAF1, high YAP1 protein levels are found in the most malignant group." (PMID 28000790, 2016). "The biochemical phenotypes observed in the autochthonous tumours could be secondary, that is, RAF1 ablation could promote the development of tumours with these molecular characteristics." (PMID 28000790, 2016). "In CRPC tumours, Raf-1 correlated with pRaf (Ser259) strongly (P=0.0003, r2=0.1778)." (PMID 21559022, 2011). "More specifically, constitutive active Raf-1 and RhoA cooperate in order to transform rat intestinal epithelial cells, providing them with a spindle-like morphology, anchorage independent growth and capacity to form tumours in athymic nude mice." (PMID 21943101, 2011). "As RAF mutations, in analogy with RAS mutations, may show tumor type specificity, we sequenced exons 11 and 15 in BRAF and the equivalent exons in ARAF (exons 10 and 13) and RAF1 (exons 11 and 14)." (PMID 21533174, 2011). "Finally, treatment of MIA PaCa-2 tumor-bearing mice with TLN-4601 resulted in antitumor activity and decreased tumor Raf-1 protein levels." (PMID 21044336, 2010). "Furthermore, TLN-4601 demonstrated PDAC cell in vivo tumor xenograft growth inhibition, which was correlated with a reduction in tumor Raf-1 levels." (PMID 21044336, 2010). "In addition, BRAF mutation may override the inhibition of Raf1 by PKA and thereby shift the balance between the tumor-promoting and tumor-suppressing effects of cAMP." (PMID 38233872, 2024). "In summary, TAF15 was found to be overexpressed in GC tumour tissues and cells and to contribute to GC malignant progression via the RAF1/MEK/ERK signalling pathway, which suggests that TAF15 might be a potential molecular diagnostic marker or therapeutic target for GC." (PMID 37037864, 2023). "Additionally, RAF1 fusions can also facilitate MAPK pathway activation in multiple tumor types." (PMID 38111008, 2023). "In summary, TAF15 is overexpressed in GC tumour tissues and cell lines, and promotes cell proliferation, migration and invasion in GC via the RAF1/MEK/ERK signaling pathway, which suggests that TAF15 might be a potential molecular diagnostic marker or therapeutic target for GC." (PMID 37037864, 2023).
tumor (continued). "In vivo experiments indicated that RAF1 could promote tumor growth and lymphatic metastasis." (PMID 35668458, 2022). "The up-regulation of RELA, AKT1, TLR1 and RAF1 and the down-regulation of MAPK9 and MAP3K8 were determined by RT-qPCR, indicating that the enhanced anti-tumor function may associate with T cell immune response and proliferation related Toll-like receptor-Akt-NF-κB signaling pathway." (PMID 35046962, 2021). "Another reason for the low tumor-plasma concordance in our study may be the too low VAF of the mutations identified in tumors for some genes (e.g., MTOR, PIK3CA, ERBB3, and RAF1), raising the question of whether they are driver mutations or just passenger variants." (PMID 34356096, 2021). "Interestingly, loss of RAF1 expression impaired tumour formation by stimulating apoptosis that is not dependent on ERK activity, suggesting that it is the loss of RAF1-mediated MST2 and ASK1 inhibition that triggers apoptosis and restrains tumour growth." (PMID 33920182, 2021). "Our study provides evidence, for the first time, that the dual inhibition of NPM-ALK and RAF1 (using pharmacological (vemurafenib) or molecular approaches (siRNA or miRNA (miR-7-5p mimics) targeting RAF1)) may be superior to single NPM-ALK targeted therapies (crizotinib) in killing tumor cells." (PMID 33066037, 2020). "Thus, RAF1 ablation in parenchymal cells led to increased inflammation in tumour-bearing livers." (PMID 28000790, 2016). "Thus, tumours with low RAF1, high YAP1 expression contain larger clusters of nuclear STAT3." (PMID 28000790, 2016). "Indeed, not only the number of tumor colonies and their size were reduced after treatment of mice with DACE, but also the amount of c-RAF-BxB protein and mRNA and the measured amounts of tumor tissue correlated very well with the amounts of expressed human c-RAF-1-BxB protein and mRNA." (PMID 25674792, 2015). "Disruption of Raf-1/ROK-alpha might provoke the differentiation of epidermal skin tumor cells, while the dissociation of Raf-1/A-Raf from ASK1 and MST2 should activate these kinases to cause apoptosis in tumor cells." (PMID 22035226, 2011). "A further example relates to an activation of the MAPK pathway, and in LC tumour biopsies, we measured an average fivefold increased phosphorylation of the peptide PRGQRDSSYYWEI at AS 332–344 of the RAF1 protein." (PMID 39995112, 2025). "Other pathways, such as Ras (RAF1, RALBP1, RASSF1), TGF-β (CREB3L2/3, CREB5, TCL1A), Rap1, Hippo, and axonal guidance, further facilitate tumour migration and spread." (PMID 41007296, 2025). "Sorafenib was found to inhibit B-Raf, Raf-1, and kinase activity in the Ras/Raf/MEK/ERK signaling pathways, thereby suppressing tumor cell proliferation, and exhibiting anti-angiogenesis and antiproliferation properties." (PMID 39921803, 2025). "The RAS protein family, known for its role in cell signaling, can influence cell death, proliferation, and metabolic stress responses through the Raf-1/MEK/ERK and Rac1/MKK7/JNK pathways, which in turn modulate tumor progression." (PMID 41040515, 2025). "Some proteins with more distant relations to the chaperone cycle (CK2, FAF1, RAF1) were still found to be contributing factors in HSP-related signaling and proteostasis processes, at the same time exhibiting involvement in tumor progression." (PMID 41369326, 2025). "The ARID1B (BAF250b) subunit is a typical nuclear tumor suppressor; however, ARID1B localized in the cytoplasm can interact with c-RAF (RAF1) and PPP1CA, thereby stimulating RAF-ERK signaling and β-catenin transcriptional activity." (PMID 39609317, 2024). "Several proteins that bind and regulate C-RAF have been identified, including RKIP (RAF1 kinase inhibitor protein), which functions as an anti-metastatic tumor suppressor and is down-regulated in various cancers." (PMID 38499327, 2024).
tumor (continued). "Regorafenib is an oral multi-targeted TKI, whose targets are involved in the regulation of tumor angiogenesis (VEGFR1–3 and TEK), oncogenesis (KIT, RET, RAF1, BRAF, and and BRAFV600E), and maintenance of the tumor microenvironment (PDGFRA, PDGFRB and FGFR)." (PMID 39165680, 2024). "All genes, except PGLYRP2, were upregulated in tumor tissues, with significant increases found for CAT (P < 0.01), CXCL1 (P < 0.05), and RAF1 (P < 0.05), which agreed with the previous results." (PMID 38806963, 2024). "Regorafenib, a novel oral multi-kinase inhibitor, disrupts kinases involved in tumor angiogenesis (VEGFR1, VEGFR2, VEGFR3, TIE2), tumorigenesis (KIT, RET, RAF1, BRAF, and BRAFV600E), and the tumor microenvironment (PDGFR and FGFR)." (PMID 39687893, 2024). "An incomplete tumor “capsule”, indicative of infiltrative tumor growth, has been identified as an imaging marker for predicting MVI and high BRAF and RAF1 expression in HCC, which can promote tumor invasion and metastasis." (PMID 38763975, 2024). "Previously, we identified 272 specific binding proteins of RAF-1; SODD was one related to the tumor process." (PMID 37107587, 2023). "In particular, RAF1 expression correlated with the expression of STAT3 targets involved in the control of angiogenesis, a crucial process necessary for tumor growth and metastasis development." (PMID 37020037, 2023). "Regorafenib is an oral multi-kinase inhibitor that targets signaling pathways involved in tumor angiogenesis (VEGFR1-3 and TIE2), oncogenesis (KIT, RET, RAF1, and BRAF), and the tumor microenvironment (PDGFR, FGFR, and CSF1R)." (PMID 37869085, 2023). "Our data first showed that TAF15 knockdown led to a significant decrease in the phosphorylation levels of RAF1, MEK and ERK1/2, while total RAF1, MEK and ERK1/2 exhibited no significant change in GC cell lines and xenograft tumours." (PMID 37037864, 2023). "Our data revealed that when tumor specimens from patients with metastatic solid cancers are subjected to NGS, approximately 2.0% of these specimens exhibit RAF1 aberrations." (PMID 38137485, 2023). "Tumor cell growth is controlled by various signaling pathways, such as PI3K/Akt and the raf-1/mitogen-regulated extracellular kinase (MEK)/extracellular regulated kinase (ERK) pathway (raf-1/MEK/ERK)." (PMID 36836894, 2023). "Another kinase inhibitor, Sorafenib (SOR), acts by inhibiting several different kinases (RAF-1, VEGF, c-KIT, PDGFR, ERK, and FLT3) involved in tumor cell proliferation and angiogenesis." (PMID 35053339, 2022). "A multivariate analysis was performed including tumor and nodal classification, grade, PAM50 subtype, NF1, KRAS, RAF1, and JUN alterations." (PMID 36358725, 2022). "Samples of P07-aRMS were obtained at the same timepoint but showed different events: the primary tumour exhibited an ATRX-deletion, whilst the metastasis harboured SNVs in ATR and RAF1, a biallelic BCOR-deletion, and a MYCN-amplification." (PMID 36182817, 2022). "Sorafenib inhibits mainly RAFs, such as RAF1 involved in the MAPK/ERK pathway, and also attenuates several tyrosine kinases, thereby suppressing tumor cell and vessel growth and growth factor production." (PMID 35659728, 2022). "However, in cancer cell lines, PDCD6 could mediate the inhibition of ASK1/JNK pathway through Raf-1 (Raf-1 protooncogene, serine/threonine kinase), thereby increasing tumor sensitivity to chemotherapy, and Raf-1 was required for MEK/2 activation under proapoptotic conditions." (PMID 36132985, 2022). "Taken together, by inhibition of RAF1 and other antiapoptotic stimuli, RKIP enhances cancer cell apoptosis directly and/or abrogates tumour cell resistance to apoptosis-enhancing stimuli." (PMID 35203304, 2022). "Proliferative tumours were characterized by high expression of the c-MET, ARID1A, CTNNB1, RAF1, LGR5, and GLUL1 genes." (PMID 36345011, 2022).